C3 (complement C3)
Diseases named in the same sentence as C3 in open-access papers (continued):
Sharing a sentence is not in itself a finding about the gene and the disease.
infection (continued). "The immune system is impaired by a C3 deficit, making the body more susceptible to infection." (PMID 35250845, 2021). "Furthermore, mice that were deficient for C3 showed increased splenic dissemination following acute intrapulmonary infection with either the hypervirulent KPPR1 strain or a CR-Kp isolate." (PMID 33558323, 2021). "Given that infection itself may be a causal event for undetectable complement, a secondary analysis excluded any C3 levels drawn within 30 days following an SBI and we found similar results." (PMID 32972440, 2020). "Further prospective studies may be needed to control for these limitations and better examine the risk of infection in patients with complement defects due to C3 consumption as SLE patients are high risk for infections." (PMID 32972440, 2020). "However, trout surviving the infection showed high expression levels of genes encoding IgT, T‐cell receptor TCRβ, C3, cathelicidins 1 and 2 and SAA, suggesting these genes to be associated with protection." (PMID 32944955, 2020). "In addition, NF-κB target genes (i.e., C3, Chi3l1, Fas, Gadd45β, Hmox1, Ptx3, Saa3, Tlr2) were abundant in the DEGs in which upregulation during infection was impaired by CCR5-deficiency." (PMID 31506064, 2019). "Second, despite the parasite's ability to inactivate C3b, in vivo studies using C3 deficient mice established that C3 is a critical factor necessary to regulate parasite proliferation and dissemination and promote a chronic, transmissible infection." (PMID 32010145, 2019). "Notably, C5aR and MAC have been ruled out as being responsible for the findings obtained with C3−/− mice, in particular for the increased susceptibility and the severe and lethal disease at the late stage of infection." (PMID 23189195, 2012). "We showed that complement C3 is important for the control of initial C. albicans burdens, but complement seems dispensable for the induction of inflammatory responses as C3-deficient mice exhibited enhanced inflammatory mediator production during infection." (PMID 23049859, 2012). "In contrast to the C3−/− mice, the C5aR−/− mice appeared to have slightly greater weight loss and worse clinical scores compared to WT mice during the early stage of high-dose infection." (PMID 23189195, 2012). "In addition, the increased susceptibility to P. aeruginosa infection observed in zebrafish deficient for c3a.1, which is homologous to the C3 component of human complement, is likely due to a neutrophil-intrinsic function of C3, possibly its ability to recruit neutrophils at the infection site." (PMID 34660345, 2021). "Given that C3 can be depleted from the local environment by S. aureus in elevated glucose, we speculated that Gram-negative bacteria susceptible to complement-mediated lysis could incur a survival advantage in polymicrobial infections." (PMID 22390383, 2012). "Therefore, by mediating infection by F. tularensis, EF-Tu – nucleolin interaction may play a role in immuno-compromised patients where C3 deficiencies are associated with higher susceptibility to severe infections." (PMID 18789156, 2008). "Relative to WT mice, C3−/− and C4−/− mice had higher bacterial loads in extra-intestinal sites (spleen, liver, and blood) at 24 hours post infection." (PMID 41279015, 2025). "Upon infection of unvaccinated mice, the C3 expression levels remained largely unaffected, whereas an increase in expression occurred in vaccinated mice, with a maximum at early patency on day 4 p.i.." (PMID 40243929, 2025). "An anti-LAMB1 antibody was used to capture LAMB1 from whole-cell lysates at 24 h post-infection, and an immunoblotting assay for C3 was performed on the pulled-down protein complexes." (PMID 40237496, 2025). "Late-stage anti-dsDNA IgM and C4 levels showed significant changes resembling those of SLE, while C3 levels remained consistent throughout the infection process." (PMID 39879248, 2025).
infection (continued). "Patients carrying this variant are predicted to experience a gain-of-function (GOF) (rs117793540) and the hyperactivation of C3 through the alternative C3-convertase pathway, disrupting the anaphylatoxin-mediated response to infection." (PMID 40724958, 2025). "Only C3 and C4 numbers increased; other clusters decreased significantly at four weeks post-infection." (PMID 40244063, 2025). "In order to ascertain the origin of the escalated complement C3 levels, we conducted staining of complement C3 with astroglia cell marker (GFAP) or microglia cell marker (Iba-1) at different time points following infection." (PMID 40294039, 2025). "In a previous study conducted by our group, we investigated the role of C3 during the acute phase of infection with L. interrogans serovar Kennewicki strain Pomona Fromm in C57BL/6 wild-type (WT) and C3-deficient (C3KO) mice." (PMID 41251377, 2025). "Consistently, epithelial, stromal, and CD45+ immune cells in the intestine did not express appreciable levels of C5–C9 transcripts, and C5 protein remains undetectable in the gut lumen, even during infection, while C3 is robustly upregulated and secreted." (PMID 41031883, 2025). "To assess the relative contributions of C3-dependent and -independent mechanisms to the CRP-driven immunity, we tested bacterial clearance of C3−/− mice with an elevated infection dose of 5 × 107 CFU, which WT mice were able to survive." (PMID 41214213, 2025). "Western blot analysis showed a significant increase in complement C1q and C3 over time during post-infection." (PMID 40294039, 2025). "This indicates that C3 serves a key regulatory function in immune responses subsequent to pathogen infection." (PMID 41463861, 2025). "Elevated levels of total flux and radiance were observed through day 6 post-infection in WT B6 mice and through day 8 in C3 KO mice infected with the Ig::Tn strain, suggesting that C3 KO mice exhibited delayed clearance of infection compared to WT B6 mice." (PMID 40586810, 2025). "Complement is a humoral factor of innate immunity and plays a crucial role in the fish immune response to pathogen infection, including C1q, C3, C5b, C6, C7, C8, C9, etc.." (PMID 41154820, 2025). "We next investigated the effect of infection on astrogliosis by measurement of the expression of complement 3 (C3, a neurotoxic reactive astrocyte marker) and S100A10 (a neuroprotective marker)." (PMID 40420159, 2025). "GLB includes immunoglobulins such as IgA, IgG, and IgM, and complements such as C3, C4, with high content and defensive function, which can enhance the body’s resistance and prevent infection." (PMID 41234405, 2025). "Recent single-cell RNA-Seq and C3-reporter assays indicate stromal cells are the main expressors of C3 in homeostasis, but epithelial cells upregulate C3 during infection." (PMID 40519170, 2025). "In a similar pattern, C3−/− mice trapped relatively fewer bacteria in the liver than WT controls at 5 min post infection." (PMID 41214213, 2025). "The optimal Multiplicity of Infection (MOI) for phage C3 is 10–3, while the optimal MOI for phage C4 is 10–4." (PMID 40552054, 2025). "Typically, cleavage of C3, C4, and C5 is critical for phagocyte recruitment to the site of infection." (PMID 39813225, 2025). "Increased expression of genes like dcs, c3, and lyz indicates the activation of innate immunity, strengthening the fish’s rapid defense against infection." (PMID 40564266, 2025). "C3 KO cells had a significantly lower NF-κB activation compared to WT and C3 ΔATG1 cells following treatment with Pam3CSK4 or infection with M. catarrhalis or LPS." (PMID 41441980, 2025). "As C3 is an essential component of the innate immune response to infection and is the point of convergence for all complement activation pathways, we examined if the absence of C3 would alter the host response to S. epidermidis CNS catheter infection." (PMID 38881889, 2024).
infection (continued). "Using our murine model of S. epidermidis catheter infection we quantified levels of the complement components C1q, Factor B, MASP2, C3, and C5 over the course of infection along with bacterial burdens." (PMID 38881889, 2024). "Following the cleavage of C3, C3a serves as an anaphylatoxin, inducing inflammation, chemotaxis, and extravasation of cells to sites of infection, while C3b binds to C4bC2a to generate the C5 convertase (C4bC2aC3b) shared by the classical and lectin pathways." (PMID 39066333, 2024). "These experiments showed that C3+/– OVA+/– MMc depletion reduced serum C3 to background levels and overturned infection resistance of C3 NIMA mice." (PMID 39541162, 2024). "We found that the C3 deposition protected host cells against infection by restricting intracellular staphylococcal growth in an ATG16L1-dependent manner." (PMID 39310788, 2024). "In fish, immune cells such as macrophages and neutrophils produce cytokines in response to pathogen infection or environmental changes, which can activate the transcription of the C3 gene." (PMID 39051347, 2024). "When FH was reduced by 75% or more, apparently complete disappearance of circulating C3 occurred after about the eighth day of the infection, leading to a prolonged suppression of the AP's ability to make C3-convertase." (PMID 38234438, 2024). "Some existing studies suggest that decreased C3 complement levels in patients with SLE are significantly related to disease activity, increased susceptibility to infection, and disease recurrence." (PMID 39087011, 2024). "Mice deficient in C3, C4, or CD21/CD35 had significantly lower IgG antibody responses and germinal centers compared to wild-type controls following infection with HSV-1." (PMID 39066333, 2024). "C3–/– mice are highly susceptible to E. coli, and an intermediate dosage (15,000 CFU) that accentuates this susceptibility was used for intravenous infection to further investigate the functional consequences of complement-producing MMcs." (PMID 39541162, 2024). "The most prevalent complement, C3, is a crucial part of innate immunity and is involved in immunological control and infection protection." (PMID 38887608, 2024). "Only C3, C4, C5 and C6 inhibited IVPs when the cells were exposed after infection, and their effect occurred in late stages after viral translation and replication, such as assembly, and not during budding." (PMID 39063216, 2024). "Complement component 3 (C3) binds the surface of T. gondii and is required for host resistance to infection." (PMID 39302131, 2024). "IgG <600 mg/dL, C3 <80 mg/dL, C4 <18 mg/dL, NK count <30 cells/μL, and CD4 count <350 cells/μL were all associated with a significantly higher risk of infection, and these five parameters were used to derive the immunological score." (PMID 39660122, 2024). "We observed a significant increase in the C3 levels on the 20th and 30th days after infection in this study." (PMID 39766497, 2024). "The degree of clotting of infected lobules (prolonging time to capsize, χ2 = 7.4, p < 0.03) and raised pre-infection C3 and FB levels (reducing time to capsize, χ2 = 21.6, p < 0.0001) were significant independent predictors." (PMID 38234438, 2024). "In fibroblasts, major differentially expressed immune-related genes included Cxcl10, Cccl7, and C3, which participate in anti-infectious immunity by immune cell recruitment during infection." (PMID 37478901, 2024). "Attention is drawn to the need to better understand the short-term dynamics of virus release into the circulation during the first 10 days of infection and their consequences for the complement response, both as they affect C3 and FH function." (PMID 38234438, 2024). "After GCRV infection, grass carp spleens demonstrated impaired complement and coagulation cascades and reduced transcription of key genes such as the C3, C5, and complement factor 7 genes, indicating GCRV’s ability to hinder these cascades in grass carp." (PMID 38666826, 2024).
infection (continued). "The mean C3 mRNA levels were observed to increase by 2.2 and 2.4-fold (p < 0.05) on the 20th and 30th days following infection with T. gondii, respectively, in comparison to the healthy control groups." (PMID 39766497, 2024). "Gelatinase contributes to virulence by degrading of collagen, fibrinogen, fibrin and certain complement components C3 and C3a which facilitate tissue invasion, impair host defenses and promote the persistence of infection." (PMID 39415105, 2024). "Other complement factors such as C5a (formed via the interaction of C3-C3b) act as a chemoattractant for the recruitment of more immune cells to the site of infection." (PMID 37434702, 2023). "MPO can modify C3, leading to its activation and the release of C3 fragments, which in turn can trigger inflammatory responses and attract immune cells to the site of infection." (PMID 37999488, 2023). "We observed complement C1q and C3 fragments (respectively, 1 and 6 peptides) decreasing during infection, and C4 changing digestion pattern with 1 peptide downregulated and 3 upregulated." (PMID 36674321, 2023). "Regarding gene expression of antimicrobial compounds, it was significantly higher in the 24 h post-infection group than in the infection group (c3, mpo, and lyso: p value < 0.001, p value < 0.01, and p value < 0.001, respectively)." (PMID 36838503, 2023). "The expression of NFATc2 and c3 in the liver of M. fortis were significantly increased at day 13 post-infection, at which time the amount of cell adherence was the greatest." (PMID 37794085, 2023). "The severity of the infection was shown by the states indicated with an asterisk (*) in the state graphs where C3 and C5a were active and PICyts was hyperactive simultaneously." (PMID 37744234, 2023). "In the present study, after a first phase of down-regulation (between 3 and 6 h post infection), c3 showed a significant increase in its expression level at 9 h post infection, returning to its basal levels at 24 h post infection." (PMID 37629124, 2023). "The functional relevance of cytosolic C3 was shown in an in vitro model of cyto‐invasive S. aureus infection, where the outcome of infection in C3‐KO cells was rescued in ∆AUG1 cells only able to express C3 within the cytosol." (PMID 36100972, 2023). "The expression of the antimicrobial compounds (c3, mpo, and lysozyme) mRNA showed a similar pattern, meaning a delayed answer after 24 h post-infection and then a return to the control state except for the mpo." (PMID 36838503, 2023). "Complement C3 mRNA levels increased in soft-shelled turtle liver after infection with Aeromonas hydrophilia in a similar manner to that reported in humans, mice, and zebrafish." (PMID 36830343, 2023). "Of the NR3055-infected C3−/− mice, 93% succumbed to infection within 50 hpi, compared to only 10% of the WT mice." (PMID 36779722, 2023). "Here we show that ISG65 is a receptor for complement C3 and affects the rate of trypanosome clearance in a mouse infection model." (PMID 36038546, 2022). "Later in the infection, C3-/- mice exhibited reduced inflammatory monocyte and neutrophil infiltration in lung tissue, reduced T-lymphocyte activation, and less edema and lung inflammation, which correlated with improved respiratory function." (PMID 35204727, 2022). "To explore the role of C3 during systemic A. fumigatus infection, we performed infection studies in C3-/- mice (C57BL/6 background) and compared it with the wild-type (WT) mice." (PMID 36211424, 2022). "Fourteen proteins, including three apolipoproteins, two globins, complement component 3 (C3), ceruloplasmin and biotinidase, were negatively correlated with the infection intensity." (PMID 36088326, 2022). "In the mouse infection models used here, the initial increase in parasite burden occurs at an equivalent rate in both C3+/+ and C3−/− mice, which suggests that the alternative and lectin-based pathways are not controlling infection." (PMID 36038546, 2022).
infection (continued). "Our study shows how S. chrysophrii infection changes the abundance of several complement proteins (factor H, factor B, factor I, C1q, C3, C4, C5, C6, C7, C8), inducing an inhibition of the alternative pathway as the infection intensity increases." (PMID 36088326, 2022). "In this study, three fibrinogen chains (Fga, Fgb and Fgg) were up-regulated in two L. monocytogenes infections, while coagulation factor X (F10) and C3 were up-regulated only in the L. monocytogenes M7 infection group." (PMID 35682909, 2022). "Increased cytokines and chemokines such as IL-6, GM-CSF, IL-1a, IL-15, CXCL9 and CXCL10 and complement system components such as C3 were also observed from 6 to 36 months after infection in patients with chronic disease compared to with retrieved controls." (PMID 36189282, 2022). "We also show that C3 contributes to control of trypanosomes during early infection in a mouse model and provide evidence that ISG65 is involved in reducing trypanosome susceptibility to C3-mediated clearance." (PMID 36038546, 2022). "Increased expression was observed more often in covid-19 patients than in uninfected donors, suggesting that cell infection induces transcription of the C3 gene." (PMID 35327350, 2022). "Here, we injected (i.p.)heat-inactivated naïve sera (to avoid any role of the complement system) from WT or C3-/- mice to C3-/- mice a day before the infection and at day 4 post-infection." (PMID 36211424, 2022). "At the high dose of conidia (1x107), all C3-/-mice succumbed to infection, but the mortality in WT mice was significantly delayed compared to C3-/- mice." (PMID 36211424, 2022). "Long MY claimed that autologous blood transfusion can increase the levels of TNF-α and complement C3 in patients, thereby enhancing their immunity against infection." (PMID 34979913, 2022). "For the complement and coagulation cascades, six differential proteins were identified in both the L. monocytogenes 10403s and M7 infection groups: Plg, Fgb, Fga, Fgg, Clu, and C3." (PMID 35682909, 2022). "We describe a novel cytosolic C3 fragment that alters S. aureus phenotype during infection of lung epithelial cells and augments subsequent phagocytosis." (PMID 35546365, 2022). "In lamprey, C3 knockdown decreased the survival rate of larvae against the infection with A. hydrophila." (PMID 35281048, 2022). "For example, in bacteria-induced lung infections, IL-22 acts on the liver to induce the expression of C3 and, thereby, modulates immune responses to control the infection." (PMID 36123595, 2022). "C3 staining in tracheal sections from mice infected with the P. aeruginosa strain NH57388A on day 1 after infection revealed a strong signal in the subepithelial layer in WT tracheae, whereas the signal in Trpm5–/– mice was less pronounced." (PMID 35503420, 2022). "Expression of the C3 complement gene was downregulated at 6 and 48 hours and upregulated at 12 and 24 hours after infection in the planktonic-infected group, whereas it was consistently downregulated after infection in the biofilm-infected group." (PMID 35677656, 2022). "Early data demonstrated elevated levels of the complement components C3 and C5at day 5 post-infection when bacterial burdens are low suggesting a role beyond control ofthe infection." (PMID 34612709, 2021). "Actually, the only obvious difference between WT➔C3−/− and C3−/−➔C3−/− BM chimeric mice was the reduced loss in body weight of the mixed chimera due to myeloid-cell-derived C3 during late stages after infection." (PMID 33746963, 2021). "Genes encoding C3, cathelicidins, lysozyme, SAA, IgM and IL-17C1 were significantly up-regulated at this late infection time-point." (PMID 34497310, 2021). "In wild-type mice, complement is activated after SARS-CoV MA15 (the mouse-adapted SARS-CoV) infection as demonstrated by elevated C3 activation products (C3 fragments C3a, C3b, iC3b, C3dg, and C3c)." (PMID 33811541, 2021).